SLAMF1 (signaling lymphocytic activation molecule family member 1)
Description:
Self-ligand receptor of the signaling lymphocytic activation molecule (SLAM) family. SLAM receptors triggered by homo- or heterotypic cell-cell interactions are modulating the activation and differentiation of a wide variety of immune cells and thus are involved in the regulation and interconnection of both innate and adaptive immune response. Activities are controlled by presence or absence of small cytoplasmic adapter proteins, SH2D1A/SAP and/or SH2D1B/EAT-2. SLAMF1-induced signal-transduction events in T-lymphocytes are different from those in B-cells. Two modes of SLAMF1 signaling seem to exist: one depending on SH2D1A (and perhaps SH2D1B) and another in which protein-tyrosine phosphatase 2C (PTPN11)-dependent signal transduction operates. Initially it has been proposed that association with SH2D1A prevents binding to inhibitory effectors including INPP5D/SHIP1 and PTPN11/SHP-2. However, signaling is also regulated by SH2D1A which can simultaneously interact with and recruit FYN which subsequently phosphorylates and activates SLAMF1. Mediates IL-2-independent proliferation of activated T-cells during immune responses and induces IFN-gamma production (By similarity). Downstreaming signaling involves INPP5D, DOK1 and DOK2 leading to inhibited IFN-gamma production in T-cells, and PRKCQ, BCL10 and NFKB1 leading to increased T-cell activation and Th2 cytokine production (By similarity). Promotes T-cell receptor-induced IL-4 secretion by CD4(+) cells (By similarity). Inhibits antigen receptor-mediated production of IFN-gamma, but not IL-2, in CD4(-)/CD8(-) T-cells (By similarity). Required for IL-4 production by germinal centers T follicular helper (T(Fh))cells (By similarity). May inhibit CD40-induced signal transduction in monocyte-derived dendritic cells. May play a role in allergic responses and may regulate allergen-induced Th2 cytokine and Th1 cytokine secretion (By similarity). In conjunction with SLAMF6 controls the transition between positive selection and the subsequent expansion and differentiation of the thymocytic natural killer T (NKT) cell lineage. Involved in the peripheral differentiation of indifferent natural killer T (iNKT) cells toward a regulatory NKT2 type (By similarity). In macrophages involved in down-regulation of IL-12, TNF and nitric oxide in response to lipopolysaccharide (LPS) (By similarity). In B-cells activates the ERK signaling pathway independently of SH2D1A but implicating both, SYK and INPP5D, and activates Akt signaling dependent on SYK and SH2D1A (By similarity). In B-cells also activates p38 MAPK and JNK1 and JNK2. In conjunction with CD84/SLAMF5 and SLAMF6 may be a negative regulator of the humoral immune response (By similarity). Involved in innate immune response against Gram-negative bacteria in macrophages; probably recognizes OmpC and/or OmpF on the bacterial surface, regulates phagosome maturation and recruitment of the PI3K complex II (PI3KC3-C2) leading to accumulation of PdtIns(3)P and NOX2 activity in the phagosomes. (Microbial infection) Acts as a receptor for Measles virus; also including isoform 4.
Synonyms: CD150; SLAM; IPO-3; IPO3; CDw150
Tractability: Antibody: UniProt places it where antibodies can reach, with high confidence; its Gene Ontology location is reachable by antibodies, with high confidence; UniProt predicts a signal peptide or a membrane-spanning region.
Gene: Protein-coding gene on chromosome 1 (160,608,100 to 160,647,044, reverse strand). Ensembl gene ENSG00000117090.
Subcellular location: Cell membrane; Secreted (Isoform 3); Cell membrane (Isoform 4)
Gene Ontology:
Molecular function: identical protein binding; protein binding; SH2 domain binding; virus receptor activity; antigen binding; signaling receptor activity; transmembrane signaling receptor activity
Biological process: myeloid dendritic cell activation involved in immune response; negative regulation of CD40 signaling pathway; negative regulation of interleukin-12 production; negative regulation of interleukin-6 production; negative regulation of tumor necrosis factor production; positive regulation of ERK1 and ERK2 cascade; positive regulation of JNK cascade; immune response; positive regulation of cell population proliferation; leukocyte activation; lymphocyte activation; natural killer cell differentiation; natural killer cell proliferation; negative regulation of cytokine production; negative regulation of T cell cytokine production; negative regulation of type II interferon production; positive regulation of activated T cell proliferation; positive regulation of T-helper 1 cell cytokine production; positive regulation of type II interferon production; symbiont entry into host cell
Cellular component: extracellular exosome; plasma membrane; external side of plasma membrane; cell surface; extracellular region; membrane; phagocytic vesicle
Genetic constraint (gnomAD): Loss-of-function variants: 6 observed, 19.48 expected, observed/expected ratio (o/e) 0.31, 90% interval 0.17 to 0.61. The upper end of that interval is the gene's LOEUF score, 0.61, which puts it in group 2 of 6, group 1 being the genes least tolerant of losing a copy. Missense variants: 265 observed, 301 expected, observed/expected ratio (o/e) 0.88, 90% interval 0.8 to 0.98. Synonymous variants: 123 observed, 115.67 expected, observed/expected ratio (o/e) 1.06, 90% interval 0.92 to 1.24.
Homologues: Orthologues: chimpanzee SLAMF1 (84% identical), macaque SLAMF1 (81% identical), rabbit SLAMF1 (70% identical), pig SLAMF1 (68% identical), dog SLAMF1 (66% identical), mouse Slamf1 (61% identical), rat Slamf1 (60% identical), guinea pig SLAMF1 (53% identical), zebrafish si:cabz01074946.1 (13% identical). Paralogues in human: LY9 (21% identical), SLAMF6 (19% identical), CD84 (19% identical), SLAMF7 (18% identical), CD244 (17% identical), SLAMF8 (16% identical), SLAMF9 (16% identical), CD2 (15% identical), CD48 (15% identical).
Diseases named in the same sentence as SLAMF1 in open-access papers:
SLAMF1 is named in the same sentence as 116 diseases in open-access papers, as found by Europe PMC text mining. Sharing a sentence is not in itself a finding about the gene and the disease. The quoted sentences say what the papers report.
measles (25 papers, 2008 to 2025). A highly contagious viral infection caused by the measles virus. "The acute phase pathogenesis of measles is primarily defined by the use of two cellular entry receptors: signaling lymphocyte activation marker F1 (SLAMF1, CD150) and nectin-4, which are expressed on myeloid, lymphoid, and epithelial cells (1, –, 3)." (PMID 38329336, 2024). "In fact, it was later found that the measles virus binds to SLAMF1 via interactions with hemagglutinin MH-V, and that SLAMF1 is a universal receptor for all morbilliviruses (of which measles is a member)." (PMID 31744090, 2019). "Monoclonal antibodies against SLAMF1, blocking the ability for measles to use this receptor as a cell entry mechanism, may prove to be a novel strategy to treat acute infection." (PMID 31744090, 2019).
viral infection (17 papers, 2011 to 2024). "Of all the SLAM family members, SLAMF1 has arguably been the most well-known association with viral infections, as it was discovered to be one of the receptors used by the measles virus to gain entry into cells." (PMID 31744090, 2019). "Feline cell receptors other than SLAMF1 and nectin-1 might bind FeMV H glycoprotein in tissues, resulting in severe viral infection." (PMID 37896864, 2023). "Notably, CD4+ T-cells in severe patients showed lower expression of the TNF superfamily ligands TNFSF10 (TRAIL) and TNFSF14 (LIGHT) and the surface protein SLAMF1 and KLRB1, all of which have roles in viral infections." (PMID 33178221, 2020). "Surprisingly, there were no overt defects in germinal center responses to acute viral infections or protein immunizations in Slamf1,5,6Δ/Δ mice, unlike Sh2d1a-/- mice." (PMID 27223891, 2016). "While blockade of SLAMF1 and SLAMF3 to directly prevent virus interactions are one approach, modulation of SLAMF9 signaling may allow for an indirect approach to treat acute or chronic viral infections." (PMID 31744090, 2019). "These cells did not express SLAMF1 and virus infections could not be blocked with antibodies against either SLAMF1 or CD46." (PMID 27657109, 2016).
chronic lymphocytic leukemia (10 papers, 2017 to 2024). "A study has demonstrated that SLAMF1 acts as a negative regulator of IL-10 expression and secretion on the surface of B cell CLL and is associated with favorable clinical outcomes." (PMID 37251372, 2023). "SLAMF1-deficient cells are resistant to drugs that activate autophagy, and these results indicate that SLAMF1 expression potentially affects drug responses in chronic lymphocytic leukemia." (PMID 34461858, 2021). "A previous study showed that a two-gene prognostic model can accurately predict the prognosis of patients with chronic lymphocytic leukemia, in which SLAMF1 is a risk gene, and patients with high risk scores had a poorer prognosis than did those with low risk scores." (PMID 33766042, 2021). "SLAMF1 is found to regulate the autophagy of patients with chronic lymphocytic leukaemia and influence the response of chronic lymphocytic leukaemia cells to autophagy‐activated therapeutics." (PMID 36802116, 2023). "And SLAMF1 could both inhibit proliferation and impair responses to B cell receptor ligation in IGHV mutated chronic lymphocytic leukemia, which was similar to the anti-tumor effect of ZC3H12D." (PMID 35090416, 2022). "Another study revealed that through selective suppression of Akt and MAPK signaling, the interaction of SLAMF1 and CD180 receptor pathways contributes to the pathobiology of B cell CLL." (PMID 37251372, 2023). "SLAMF1 and CD180 are considered positive CD20 expression regulators that may promote the responsiveness of SLAMF1+CD180+ B cell CLL to cancer immunotherapies based on CD20 targeted therapy." (PMID 37251372, 2023). "SLAMF1 level is down‐regulated in chronic lymphocytic leukaemia and has an independent negative prognostic effect on overall survival in chronic lymphocytic leukaemia." (PMID 36802116, 2023). "On the other hand, all analyzed cases of small lymphocytic lymphoma (SLL) (seven out of seven), lymphoplasmacytic lymphoma (LPL) (two out of two), and sporadic Burkitt lymphoma (three out of three) were SLAMF1/CD150-negative." (PMID 38612827, 2024).
leukemia (10 papers, 2010 to 2025). A malignant (clonal) hematologic disorder, involving hematopoietic stem cells and characterized by the presence of primitive or atypical myeloid or lymphoid cells in the bone marrow and the blood. "Slamf1 (Signaling lymphocytic activation molecule family member 1), Snca (Synuclein alpha) and Btbd14a (BTB/POZ domain containing 14A) are higher expressed in the erythroleukaemias and lower in the megakaryoblastic leukaemias but were also amplified in other types of leukaemias." (PMID 20102610, 2010).
autoimmune disease (9 papers, 2014 to 2025). A disorder resulting from loss of function or tissue destruction of an organ or multiple organs, arising from humoral or cellular immune responses of the individual to their own tissue constituents. "Many of these genes have either known roles in Treg differentiation, stability and function (CD48, IL6ST, EZR, ELMO1, IL18R1), or altered expression in human Treg in autoimmune disease (SLAMF1, ANKRD55, TAGAP)." (PMID 35773720, 2022). "We observed that, among all the populations of interest identified in the cohort 1, only B cells-expressing SLAMF1 (identified as SLEB1) were significantly increased in SLE compared to healthy and autoimmune diseases controls." (PMID 35603218, 2022).
systemic lupus erythematosus (9 papers, 2008 to 2025). An autoimmune multi-organ disease typically associated with vasculopathy and autoantibody production. "SLAMF1 has been associated with several disease processes in humans, including rheumatoid arthritis, systemic lupus erythematosus, and diabetes." (PMID 40612147, 2025). "SLAMF1 is overexpressed on the T cell, B cell and their subgroups of Systemic lupus erythematosus (SLE) patients." (PMID 32746852, 2020). "Previous studies of Slamf1-/- and Slamf6-/- mice that were backcrossed to C57Bl/6 mice have used lupus-prone (129 x B6) Sle1b mice as WT controls, due to residual 129-derived sequences around the SLAM loci, which were mutated in 129 ES cells." (PMID 27258160, 2016). "By contrast, other SLAMF receptor-deficiencies embedded in the BALB/c genome, such as Slamf1−/−(BALB/c.129) and Slamf2−/−(BALB/c.129), do not develop any autoimmune response, underscoring the role played by Ly9 as a negative regulator in the pathogenesis of lupus." (PMID 23914190, 2013).
rheumatoid arthritis (8 papers, 2019 to 2025). A chronic, systemic autoimmune disorder characterized by inflammation in the synovial membranes and articular surfaces. "For three of these genes—CD5, CTLA4, and SLAMF1—associations of rheumatoid arthritis with SNPs within 200 kb of the transcription site are listed in the GWAS catalog." (PMID 39887658, 2025). "This protein has been previously associated with autoimmunity, as an increased expression of SLAMF1 on peripheral and tissue-resident lymphocytes from patients with rheumatoid arthritis and systemic lupus erythematous have been reported." (PMID 32983115, 2020). "Signaling lymphocytic activation molecule family member 1 (SLAMF1) modulates rheumatoid arthritis pathogenesis by orchestrating inflammatory cascades via infiltrating immune cells." (PMID 40509092, 2025). "SLAMF1 is overexpressed in myeloid cells from patients with Crohn's disease and in T lymphocytes from patients with rheumatoid arthritis." (PMID 31824496, 2019). "For five of the 16 putative core genes—CD5, CTLA4, SLAMF1, PDCD1, and TNFRSF14—that were identified through association of GATE scores with rheumatoid arthritis, associations of rheumatoid arthritis with SNPs within 200 kb of the transcription site are listed in the GWAS catalog." (PMID 39887658, 2025).
breast carcinoma (7 papers, 2016 to 2024). "Furthermore, it was found that the SLAMF1 single nucleotide polymorphism (SNP) rs1061217 was associated with a decreased risk of breast cancer in overweight women, while it increased the risk of breast cancer in those with normal weight." (PMID 38476238, 2024). "In breast cancer, the high expression of SLAMF1, SLAMF7, CD48, and IGLL1 is positively correlated with the infiltration of B cells, CD8 + T cells, CD4 + T cells, macrophages, neutrophils, and dendritic cells." (PMID 38388382, 2024). "The results showed that IGLL1, SLAMF7, SLAMF1, CD48, and LRRC8A were closely associated with immune infiltration in breast cancer (p < 0.05)." (PMID 38388382, 2024). "On the other hand, CD48, SLAMF1, and SLAMF7 were highly expressed in HER2 + and triple-negative breast cancer (TNBC), and IGLL1 was highly expressed in ER + and TNBC tissues; These six key genes are closely associated with immune infiltration in breast cancer." (PMID 38388382, 2024). "Comparing the gene expression between normal breast epithelial cells and four types of breast cancer cells, it was found that all four different types of breast cancer cells exhibited differential expression of theHERV-K_1q23.3, SLAMF1, HERV-K_22q11.23, IGLL1, HERV-K_9q34.11 and LRRC8A." (PMID 38388382, 2024). "We evaluated the correlation between the expression of IGLL1, SLAMF7, SLAMF1, CD48, and LRRC8A and the immune infiltration profile in breast cancer using data downloaded from TCGA." (PMID 38388382, 2024). "A total of 88 candidate genes related to breast cancer prognosis were screened, of which CD48, SLAMF7, SLAMF1, IGLL1, IGHA1, and LRRC8A were key genes." (PMID 38388382, 2024). "In three different types of breast cancer cells, differential expression was also observed in genes including HERV-K_1q23.3, CD48, SLAMF1, SLAMF7, HERV-K_22q11.23, IGLL1, HERV-K_9q34.11, and LRRC8A." (PMID 38388382, 2024). "A study reveals no expression of SLAMF1 on the cell surface membrane in breast cancer cell lines, while the prostate cancer cell lines expressed SLAMF1 both in the cytoplasm and on the cell surface." (PMID 37251372, 2023). "Further research is needed to investigate these results, and the results of the drug sensitivity analysis indicated that IGLL1, SLAMF7, SLAMF1, CD48, and LRRC8A might decrease sensitivity to specific chemotherapy drugs, further affecting the treatment efficacy for breast cancer." (PMID 38388382, 2024).
multiple myeloma (6 papers, 2017 to 2025). "For instance, SLAMF1/CD150 is differentially expressed in various hematologic cancers, including chronic lymphocytic leukemia (CLL) and multiple myeloma, suggesting its potential as a prognostic marker." (PMID 41162970, 2025).
tuberculosis (5 papers, 2017 to 2025). A chronic, recurrent infection caused by the bacterium Mycobacterium tuberculosis. "Evidence has been suggested that SLAMF1 is involved in neutrophil autophagy during active tuberculosis." (PMID 36802116, 2023). "Interestingly, they also demonstrated that IL-17 and SLAMF1 have opposing effects on IFNγ production in tuberculosis patients." (PMID 29434592, 2018). "SLAMF1 (Signaling Lymphocytic Activation Molecule Family Member 1) protein can identify early or paucibacillary tuberculosis in Sputum Culture-Negative Pulmonary Tuberculosis patients, serving as an essential inflammatory factor that predicts negative pulmonary tuberculosis." (PMID 40164948, 2025).
COVID-19 (4 papers, 2021 to 2025). A disease caused by infection with severe acute respiratory syndrome coronavirus 2. "After adjustment for confounding factors, seven proteins that were highly abundant and associated with an increased hazard of critical COVID-19 outcome were SLAMF1, CCL25, IL2RB, IL10RA, IL15RA, IL18 and CST5." (PMID 40475767, 2025). "Here, we demonstrated that the unique signature featuring SLAMF1, CCL25, IL2-RB, IL10RA, IL15RA, IL18, and CST significantly increased the risk of critical illness in COVID-19 patients." (PMID 40475767, 2025). "Protein levels of SLAMF1, IL15RA, and IL18 associated with critical illness during the acute phase of COVID-19 also predicted Long COVID risk." (PMID 40475767, 2025). "Notably, baseline protein levels of SLAMF1, IL15RA and IL18 associated with the critical illness during the acute phase of COVID-19 were also able to predict Long COVID risk." (PMID 40475767, 2025). "Interestingly, elevated levels of three proteins, namely SLAMF1, IL18 and IL15RA were associated with the risk of developing critical COVID-19 and Long COVID." (PMID 40475767, 2025). "Subgroup analyses of the five deceased COVID-19 patients (all males) revealed significantly upregulated proteins such as CD8A, SLAMF1 and LIF-R, HGF, CCL25, NT3 compared to the surviving patients." (PMID 37832397, 2023). "Levels of SLAMF1, CCL25, IL2RB, IL10RA, IL15RA, IL18 and CST5 were significantly upregulated in patients with critical COVID-19 illness compared to individuals negative for COVID-19." (PMID 40475767, 2025). "We identified that only three proteins, namely TNF, SLAMF1, and CDCP1, were differentially abundant in critically ill COVID-19 patients compared to those with non-critical illness presentation." (PMID 40475767, 2025).
B cell lymphomas (3 papers, 2020 to 2024). "SLAMF1 was highly expressed in Farage cells, which is an EBV positive B cell lymphoma cell line." (PMID 32886706, 2020).